RAD51 (RAD51 recombinase)
Diseases named in the same sentence as RAD51 in open-access papers (continued):
Sharing a sentence is not in itself a finding about the gene and the disease.
ovarian carcinoma (149 papers, 2006 to 2026). A malignant neoplasm originating from the surface ovarian epithelium. "Previous studies have shown that overexpression of RAD51 in various cancers, including esophageal adenocarcinoma, colon cancer, breast cancer, and ovarian cancer, is associated with drug resistance, immune evasion, and a poor prognosis." (PMID 41199843, 2025). "RAD51 overexpression has been implicated in various cancers, including colon, breast, and ovarian cancers, and is strongly correlated with tumor progression and poor prognosis." (PMID 41199843, 2025). "While BRCA1 and RAD51 germline mutations are well-characterised in breast and ovarian cancer, their role in renal cell carcinoma is still largely unexplored." (PMID 38512353, 2024). "Similar to ovarian cancer, the expression of RAD51 was remarkably downregulated in KDM1A deficient TE1 and K410 cells (p < 0.0001), whereas it was highly upregulated in KDM1A overexpressing OE19 cells (p = 0.0058)." (PMID 39638799, 2024). "Mutations in RAD51 have been associated with an increased susceptibility to certain types of cancer, particularly breast and ovarian cancer." (PMID 37958970, 2023). "Recently Hoppe and colleagues reported that high RAD51 nuclear expression scores associate with worse platinum response in ovarian cancer." (PMID 36805632, 2023). "RAD51 protein expression was increased in C13K cells compared to the chemosensitive OV2008 epithelial ovarian cancer cell line and was also associated with decreased survival in patient-derived tissue samples." (PMID 36551731, 2022). "RAD51 expression profile, target-disease associations, and fitness scores of RAD51 were analyzed in ovarian cancer using bioinformatic analysis." (PMID 33952262, 2021). "The unfavorable role of RAD51 was further supported by the general target-disease associations of RAD51 with ovarian cancer." (PMID 33952262, 2021). "Among the 31 diseases associated with RAD51, which scored higher than 0.5, ovarian neoplasm, ovarian carcinoma, ovarian adenocarcinoma, and ovarian serous adenocarcinoma were confirmed." (PMID 33952262, 2021). "Nevertheless, both FA syndrome and familial breast and ovarian cancer reveal the association of HR gene germline mutations with cancer susceptibility, with the exception of the central HR player RAD51." (PMID 34316706, 2021). "BRCA1 and BRCA2, both of which help maintain genomic stability and are significantly mutated in ovarian cancer, directly interact with RAD51." (PMID 33952262, 2021). "Misregulation of RAD51, and its regulators, is associated with FA-like syndrome and cancer, particularly breast and ovarian cancers." (PMID 33015624, 2020). "We previously reported that induction of nuclear RAD51 foci by PARPi olaparib was significantly attenuated by CHK1i Prex in ovarian cancer cells, thus sensitizing BRCAwt HGSOC to PARPi via causing an HR-deficient phenotype." (PMID 32647134, 2020). "While RAD51 mutations are associated with many cancer types, mutations in genes that regulate RAD51 are more closely associated with breast and ovarian cancers." (PMID 33015624, 2020). "The downregulation of BRCA2 reduces the expression of the homologous recombination (HR) pathway-associated RAD51 protein and suppresses DNA repair in ovarian cancer cells, sensitizing them to cisplatin." (PMID 32404140, 2020). "Recently, a variety of studies have focused on the association between the 135G/C polymorphism in the RAD51 gene and ovarian cancer." (PMID 30712190, 2019). "The search for markers of ovarian cancer development was carried on in the further part of the study by an analysis of the polymorphisms of HR genes (RAD51 and BRCA1)." (PMID 30712190, 2019). "The studies successfully demonstrated that 135C allele of RAD51 gene 135G/C polymorphism was correlated with an increased risk of ovarian cancer in the studied population (OR 5.16; 95% CI 4.29–6.20, p < 0.001)." (PMID 30712190, 2019).
ovarian carcinoma (continued). "In the Finnish population, recurrent founder mutations have been observed in many of the known breast and ovarian cancer susceptibility genes, including the RAD51 paralogs RAD51C and RAD51D." (PMID 27149063, 2016). "The data are in line with a recent study showing that ART causes a reduction in the Rad51 level in ovarian cancer cells thus sensitizing them to cisplatin." (PMID 27626497, 2016). "The most common examples are represented by the inactivating mutations in BRCA1/2 and RAD51 in breast and ovary cancer." (PMID 26295265, 2015). "Of note, even sublethal concentrations of 17-AAG had a significant functional impact on HR causing approximately 70% reduction in RAD51 foci formation in HR proficient ovarian cancer cell lines." (PMID 24798692, 2014). "A very recent study identified homologous recombination-deficient epithelial ovarian cancers via a RAD51 foci analysis on primary cultures from ascitic fluid." (PMID 23344037, 2013). "It confirms that RAD51 paralog mutations confer breast and ovarian cancer predisposition and are rare events." (PMID 24139550, 2013). "This study identified the first RAD51B mutation in a breast and ovarian cancer family and confirmed that RAD51 paralog mutations confer breast and ovarian cancer predisposition and are rare events." (PMID 24139550, 2013). "Recent studies conducted on RAD51 paralogs, involved in the same DNA repair pathway, have identified rare germline mutations conferring breast and/or ovarian cancer predisposition in the RAD51C, RAD51D and XRCC2 genes." (PMID 24139550, 2013). "The connection described here between HELQ and the RAD51 paralogs suggests that HELQ is a candidate gene for loss or mutation in sporadic or inherited ovarian cancer." (PMID 24005565, 2013). "A large case-control mutation screening study focusing on ovarian cancer would also be warranted to investigate the implication of RAD51 in ovarian cancer susceptibility." (PMID 23300655, 2012). "Rappako and colleagues recently used conformation-sensitive gel electrophoresis to screen 74 high-risk and 52 moderate-risk Finnish breast and/or ovarian cancer families for variation in the RAD51 gene." (PMID 16762046, 2006). "A low level of RAD51-positive cells in proliferating tumors has been shown to be associated with HR deficiency and to correlate with olaparib sensitivity in breast and ovarian carcinoma." (PMID 39039067, 2024). "In patients with ovarian cancer, a PARPi response was linked to a low RAD51 score." (PMID 36836518, 2023). "In another study, 1.5% (3/207) RAD51 mutations were identified in Japanese ovarian cancer patients." (PMID 35608067, 2022). "The top 20 targets related to RAD51 and RAD51 were all implicated in ovarian cancer." (PMID 33952262, 2021). "Quantitative immunohistochemistry (qIHC) reveals that high expression of the DNA repair protein RAD51 in epithelial ovarian cancer (EOC) is associated with early relapse after platinum chemotherapy, and also with decreased cytotoxic T‐cell infiltration into tumors." (PMID 33709473, 2021). "RAD51 had extensive target-disease associations with various diseases, including ovarian cancer." (PMID 33952262, 2021). "Furthermore, Rad51 dysregulation has also been linked to variety of tumors, including pancreatic cancer, colorectal cancer, and ovarian cancer." (PMID 34115569, 2021). "RAD51 had target-disease associations with ovarian cancer and conferred ovarian cancer dependency." (PMID 33952262, 2021). "RAD51 significantly correlated with six highly mutated genes in ovarian cancer and formed a regulatory network by protein–protein interactions, thereby being involved in ovarian tumorigenesis and associated with ovarian cancer." (PMID 33952262, 2021). "By forming a complex regulatory network, RAD51 closely associated with ovarian cancer." (PMID 33952262, 2021). "RAD51 conferred ovarian cancer dependency and was associated with ovarian cancer." (PMID 33952262, 2021).
ovarian carcinoma (continued). "The target-disease associations of RAD51 were assessed to evaluate its role in ovarian cancer." (PMID 33952262, 2021). "Deletion of C-terminal region of BRCA2 or mutants like BRCA2 6174delT and 6158insT impair the RAD51- binding activity of this domain, diminish the RAD51 recruitment to the damage site, and thereby increase the risk of tumor incidence in mice and early onset of breast and ovarian cancers in human." (PMID 33013205, 2020). "Moreover, this miRNA has been linked to DNA damage response by repressing RAD51 expression in ovarian cancer cells." (PMID 31191653, 2019). "Importantly, mutations in the RAD51 paralogs are highly associated with hereditary breast and ovarian cancer predisposition, and more recently with several other cancers, including melanoma, colon, and pancreatic cancers." (PMID 30551670, 2018). "Up to now, a variety of molecular epidemiological studies have been conducted to estimate the association between the RAD51 135G/C polymorphism and risk of various cancers, including squamous cell carcinoma of the head and neck, colorectal cancer, ovarian cancer and acute leukaemia." (PMID 24457040, 2014). "Sublethal concentrations of 17-AAG (as determined by 17-AAG dose response curves that were obtained for each ovarian cancer cell line) had a significant impact on RAD51 foci after IR causing approximately 70% reduction in foci formation in 36M2 and SKOV3 cells." (PMID 24798692, 2014). "Further, the association with RAD51 paralogs suggests HELQ as a candidate ovarian cancer gene." (PMID 24005565, 2013). "Our investigation showed that DHS is superior to resveratrol in downregulating of RAD51 expression and inducing replication stress in ovarian cancers." (PMID 40089867, 2025). "The expression rate of RAD51 protein in ovarian cancer tissues was significantly higher compared to normal ovarian tissues (95.3%VS 16.7%, P < 0.05)." (PMID 41199843, 2025). "It was showed that a high level of RAD51 attribute to chemoresistance in ovarian cancer and soft tissue sarcoma." (PMID 39865088, 2025). "This study highlighted the essential role of histone and RAD51 lactylation in HR repair and platinum resistance of ovarian cancer." (PMID 40083924, 2025). "It was reported that miR-506 sensitizes ovarian cancer cells to platinum treatment through directly targeting RAD51." (PMID 39865088, 2025). "Future research should focus on the development of targeted therapies targeting RAD51, with the goal of enhancing chemotherapy sensitivity by down-regulating RAD51 expression, ultimately improving survival outcomes for patients with ovarian cancer." (PMID 41199843, 2025). "Disruption of DNA repair protein RAD51 in ovarian cancer cells also leads to G2/M arrest, excessive accumulation of dysfunctional mitochondria and mitochondrial superoxide." (PMID 40163489, 2025). "For instance, in the context of homologous recombination deficiency (HRD), RAD51 foci can guide the use of PARP inhibitors (PARPis) in patients without mutations in HR-related genes suffering from breast and ovarian cancer." (PMID 40710361, 2025). "Our results revealed that treatment of SK‐OV‐3 cells, epithelial human ovarian carcinoma, with these resveratrol analogues (10 μM, 24 h) led to differential expression of RAD51." (PMID 40089867, 2025). "Given the expanding therapeutic potential of PARPi beyond ovarian cancer, it will be interesting to validate the RAD51 IHC test in other cancer types, such as breast, prostate, and pancreatic cancer." (PMID 38725623, 2024). "In ovarian cancer, one of the earliest studies examined RAD51 IF expression after irradiating patient-derived primary cells to predict primary chemotherapy response and survival." (PMID 38725623, 2024). "This study aimed to investigate the potential of RAD51 IHC in predicting de novo and acquired resistance in patients with ovarian cancer who had received PARPi." (PMID 38725623, 2024).
ovarian carcinoma (continued). "Carboplatin/olaparib plus AVB-500, a selective inhibitor of GAS6-AXL, can increase DNA damage and RAD51 focus formation and slow replication fork progression, resulting in rapid death of ovarian cancer cells in vitro and decreased tumor burden in vivo." (PMID 38539161, 2024). "miR-506, miR-103 and miR-107 are robust clinical markers for the chemotherapy response and survival in patients with ovarian cancer and can sensitize cancer cells to DNA damage by directly targeting RAD51 and inhibiting the formation of RAD51 foci." (PMID 38539161, 2024). "RAD51 is a potential functional IHC biomarker of de novo and acquired PARPi resistance in BRCA-mutated ovarian cancer and can be used to fine-tune ovarian cancer treatment." (PMID 38725623, 2024). "Most recently, its inhibition was found to increase the sensitivity of HRR proficient ovarian cancers to PARPi by downregulating RAD51 and BRCA1/2." (PMID 39638799, 2024). "We investigated RAD51 immunohistochemistry (IHC) as a functional biomarker for predicting PARPi sensitivity in ovarian cancer." (PMID 38725623, 2024). "Previous studies suggested that XRCC3 rs861539, XRCC2 rs718282, XRCC2 rs3218536, BRCA1 rs1799950, RAD51 rs1801320 and LIG4 rs10131 were associated with the risk of ovarian cancer." (PMID 38890669, 2024). "assessed RAD51 IF across different time points in newly diagnosed ovarian cancer patients receiving neoadjuvant chemotherapy." (PMID 38725623, 2024). "Recruitment of RAD51 to DNA lesion sites has been proposed as a biomarker of HR proficiency in ovarian cancer cells." (PMID 37048111, 2023). "In ovarian cancer cells, the depletion and inhibition of RAD51 lead to a significant increase in ROS, particularly in the mitochondria, underscoring the role of RAD51 in regulating mitochondrial oxidative stress." (PMID 37107181, 2023). "At the same time, induction of hypoxia via inhibition of VEGF is associated with downregulation BRCA1/2 and RAD51, in BRCA1/2 wild-type ovarian cancer cell lines." (PMID 37430137, 2023). "Next, we examined the changes of BRCA1, BRCA2, ATM, and RAD51, key genes of HR repair pathway, in MEnZn‐CuO NPs‐treated ovarian cancer cells." (PMID 37206208, 2023). "A sequential combination of crizotinib and a PARPi resulted in activation of ATM/CHK2 and inhibition of c-Met pathways, contributing to a decrease in RAD51 levels and induced apoptotic cell death in ovarian cancer cell lines." (PMID 37430137, 2023). "Our group recently published that the RAD51 foci score predicted olaparib sensitivity in a panel of patient-derived ovarian cancer xenografts (the lower the RAD51 foci score, the greater olaparib response)." (PMID 37686585, 2023). "RAD51 paralogs (RAD51B, RAD51C, RAD51D, XRCC2, and XRCC3) have recently been involved in breast and ovarian cancer predisposition." (PMID 36544182, 2022). "Then, we focused on genes traditionally associated with breast/ovarian cancer or other malignancies, and identified 23 missenses, 2 splicing, and 2 UTR variants mainly affecting genes involved in DNA repair, such as RAD51, RAD54B, PMS1, FANCD2, XRCC1, and BLM." (PMID 35893033, 2022). "In ovarian cancer, Rad51 depletion exhibits accumulation of mtROS and impaired mitochondrial membrane potential." (PMID 35875146, 2022). "In another study evaluating the contribution of RAD51 genes, small proportions of pathogenic mutations in RAD51C (14/3429, 0.41%) and RAD51D (12/3429, 0.35%) in invasive epithelial ovarian cancer were identified." (PMID 35608067, 2022). "Basal Rad51 foci score acts as a candidate predictive biomarker of olaparib response in ovarian cancer patient-derived xenografts." (PMID 35875146, 2022). "While exploring the function of microRNA ler-7e in ovarian cancer, Xiao and colleagues observed that RAD51 contributes to chemotherapeutic resistance using the chemoresistant epithelial ovarian cancer cell line C13K." (PMID 36551731, 2022).
ovarian carcinoma (continued). "In epithelial ovarian cancer, high expression of Rad51 has been found to be correlated with early relapse after platinum-based regimens and impaired cytotoxic T cell infiltration." (PMID 35875146, 2022). "Disruption of mitochondrial homeostasis similarly occurs in ovarian cancer cells in which RAD51 is depleted." (PMID 34773075, 2022). "High RAD51 expression implies unfavorable survival prognosis and suggests decreased drug responsiveness in ovarian cancer patients." (PMID 33952262, 2021). "By enrichment analysis, 557 genes correlated with RAD51 in TCGA ovarian cancer were significantly accumulated in Gene Ontology and KEGG pathways involved in DNA damage repair and drug responsiveness." (PMID 33952262, 2021). "Together, ovarian cancer expresses more RAD51 than normal ovary, and RAD51 affects the prognosis of ovarian cancer patients." (PMID 33952262, 2021). "To further confirm the role of RAD51 in ovarian cancer, we detected RAD51 immunohistochemically in a cohort encompassing 126 ovarian cancer patients." (PMID 33952262, 2021). "RAD51 is overexpressed in high-grade serous ovarian cancer, and depletion of RAD51 results in G2/M arrest in ovarian cancer cells." (PMID 34716319, 2021). "We then examined RAD51 expression in 17 datasets using Oncomine, and RAD51 was found to be significantly overexpressed in ovarian cancers (P = 0.028)." (PMID 33952262, 2021). "In our validation cohort, high RAD51 expression indicated platinum resistance in ovarian cancer patients, and platinum-sensitive cancers expressed significantly less RAD51." (PMID 33952262, 2021). "RAD51 expression in cancers was profiled to get a general insight and its expression in ovarian cancer was then studied in detail." (PMID 33952262, 2021). "Ovarian cancer patients with normal RAD51 gene were inclined to experience new neoplasm events post initial therapy." (PMID 33952262, 2021). "M. Sprick, J. Schwickert and F. Zickgraf discuss the identification of RAD51 as a biomarker of platinum resistance in High‐Grade Serous Ovarian Cancer patients, as reported by A. Jeyasekharan and colleagues in this issue of EMBO Molecular Medicine." (PMID 33779077, 2021). "Though mutations or methylation of RAD51 and ATM alterations were identified associated with PARPi responses in ovarian cancer patients, the extent to which other candidate HRR related genes impact PARPi response is still under investigation." (PMID 34702316, 2021). "Consistently, high RAD51 expression deteriorated survival outcomes of ovarian cancer patients in GSE26193 (OS, HR = 2.04, P = 0.013; PFS, HR = 1.91, P = 0.023)." (PMID 33952262, 2021). "Although RAD51-targeted therapies are still in the preclinical study or clinical trial phase, it is reasonable to believe that RAD51 is potentially a potent therapeutic target in ovarian cancer." (PMID 33952262, 2021). "Survival analysis and drug sensitivity assay were performed to evaluate the effect of RAD51 expression on ovarian cancer prognosis." (PMID 33952262, 2021). "Mutational analysis of RAD51 in 125 families from 12 countries across Europe and North American found an association between RAD51C/D mutations and increased risk of ovarian cancer (RAD51C: p < 0.001, RAD51D: p < 0.001)." (PMID 34711195, 2021). "High RAD51 expression predicted poorer survival in ovarian cancer patients and indicated drug tolerance, including platinum, taxane, and PARP inhibitors." (PMID 33952262, 2021). "More patients with unaltered RAD51 had experienced new neoplasm events post initial therapy, suggesting a possibly deleterious role of RAD51 in ovarian cancer." (PMID 33952262, 2021). "Robust and well controlled studies to evaluate and improve the RAD51/geminin score evaluation system also need to be carried out in ovarian cancer." (PMID 34702316, 2021). "The effect of RAD51 expression on survival and drug responsiveness in ovarian cancer was examined in online databases." (PMID 33952262, 2021).